VCP (valosin containing protein)
Diseases named in the same sentence as VCP in open-access papers (continued):
Sharing a sentence is not in itself a finding about the gene and the disease.
mast cell tumors (1 paper, 2024). "Interestingly, dogs commonly present with mast cell tumors in the skin, suggesting the efficacy of VCP inhibitors in such tumors as well." (PMID 38727283, 2024).
memory impairment (1 paper, 2021). "Moreover, approximately a third of patients with VCP mutations also display memory loss, and we found that two of nine mutants (P134L and A436S) displayed memory impairments." (PMID 34160014, 2021).
metastatic melanoma (1 paper, 2021). A melanoma that has spread from its primary site to another anatomic site. "In the first study, a proteomic analysis revealed the overexpression of VCP/p97 upon irradiation of the human metastatic melanoma cell line BLM, which was potentially associated with a survival mechanism." (PMID 34576340, 2021).
monoclonal gammopathy of undetermined significance (1 paper, 2023). "Initially, we examined VCP expression in normal plasma (NP, n = 22), monoclonal gammopathy of undetermined significance (MGUS, a pre-MM disease, n = 44) and MM samples (n = 351) from gene expression profiling (GEP) database." (PMID 37606987, 2023).
Neurodegeneration (1 paper, 2020). Progressive loss of neural cells and tissue. "Mitochondrial function is also found to be disturbed by VCP mutations in neurodegeneration diseases like ALS and IBMPFD, including the increased mitochondrial fragmentation, the loss of mitochondrial membrane potential and the increased reactive oxygen species (ROS)." (PMID 32481679, 2020).
Onset (1 paper, 2022). The age group in which disease manifestations appear. "Consistent with the important roles of p97/Cdc48/VCP in eukaryotic cell biology, dominant mutations in human p97 are associated with a late-onset multisystem proteinopathy, whilst p97 is upregulated in certain cancer types and is a target for anti-cancer therapies." (PMID 35920641, 2022).
oropharyngeal carcinoma (1 paper, 2025). Carcinoma, predominantly squamous cell, arising from the epithelial cells of the oropharynx. "In HPV negative oropharyngeal carcinomas, a significantly improved disease-free survival was demonstrated with high VCP/p97 expression." (PMID 41357812, 2025). "Furthermore, VCP/p97 has been reported to have prognostic significance in esophageal, gastric, prostate, pancreatic, follicular thyroid, gingival, breast, bronchial and HPV negative oropharyngeal carcinomas." (PMID 41357812, 2025).
osteoporosis (1 paper, 2025). A condition of reduced bone mass, with decreased cortical thickness and a decrease in the number and size of the trabeculae of cancellous bone (but normal chemical composition), resulting in increased fracture incidence. "Molecular docking results indicated that MEHP may influence osteoporosis by interacting with three proteins: CTSD, VCP, and SOAT." (PMID 40969353, 2025).
poliovirus infection (1 paper, 2022). An disease or disorder caused by infection with Enterovirus C. "In HCV and poliovirus infection, VCP has been identified as a cellular factor that facilitates viral genome replication." (PMID 35063505, 2022).
preeclampsia (1 paper, 2020). Preeclampsia is a hypertensive disorder of pregnancy that is characterized by new-onset hypertension with proteinuria presenting after 20 weeks of gestation, and depending on mild or severe forms may initially present with severe headache, visual disturbances, and hyperreflexia. "Therefore, the dysfunction of p97/Valosin-containing protein might be worthy of remark on preeclampsia." (PMID 32392703, 2020).
psoriasis (1 paper, 2024). An autoimmune condition characterized by red, well-delineated plaques with silvery scales that are usually on the extensor surfaces and scalp. "FABP5 interacts with VCP, which is a crucial player in NF-κB activation, and their silencing inhibits NF-κB signaling and neutrophil chemotaxis, suggesting a role in the molecular mechanisms underlying psoriasis pathogenesis." (PMID 38892253, 2024).
respiratory failure (1 paper, 2023). The significant impairment of gas exchange within the lungs resulting in hypoxia, hypercarbia, or both, to the extent that organ tissue perfusion is severely compromised. "Another missense variant at the same residue (NM_007126.5, c.266G>A; p.Arg89Gln) in the VCP gene has been reported in a Chinese patient with young-onset ALS, who died of respiratory failure 5 months after the onset of initial symptoms." (PMID 37303947, 2023).
sarcopenia (1 paper, 2020). Progressive decline in muscle mass due to aging which results in decreased functional capacity of muscles. "The expression of VCP/p97 is induced during sarcopenia, while the dominant-negative inhibition of VCP/p97 in the mouse muscle resulted in reduced fiber atrophy induced by starvation and denervation." (PMID 32859116, 2020).
schistosomiasis (1 paper, 2024). An infectious disease caused by parasitic trematodes of the genus Schistosoma that colonize human blood vessels and release eggs that can cause granulomatous reactions leading to acute (swimmer's itch or acute schistosomiasis syndrome) or chronic disease. "Further research is needed to elucidate the precise role of VCP/P97 in the pathogenesis of schistosomiasis." (PMID 38720339, 2024). "This suggests that VCP not only functions in host immune evasion in the final host mammal but also plays a key role in the establishment of schistosomiasis in the intermediate host." (PMID 38720339, 2024).
Sepsis (1 paper, 2010). Sepsis is defined as life-threatening organ dysfunction caused by a dysregulated host response to infection. "We also observed a constitutive change in accumulation of ubiquitinated proteins and VCP expression in the liver of adult mice compared to the pediatric that was further amplified by CLP induced sepsis." (PMID 21085581, 2010).
Stroke (1 paper, 2019). Sudden impairment of blood flow to a part of the brain due to occlusion or rupture of an artery to the brain. "However, literature retrieval results showed little evidences that other hub genes MPP4, RRM2, RRM2B, RRM1 and VCP contributed to the molecular mechanism of stroke prognosis." (PMID 31690277, 2019).
T-cell lymphomas (1 paper, 2015). "VCP expression in T-cell lymphomas on the other hand did not vary significantly according to grade." (PMID 26104798, 2015).
uterine cancer (1 paper, 2023). Primary or metastatic malignant neoplasm involving the uterine corpus and/or the cervix. "Mutations of PPP2R1A in uterine cancer affect oncogenic signaling and promote tumor cell growth, whereas EHHADH and ACAT1 are regulators of drug resistance in tumor cells; however, the role of VCP in cancer is unclear." (PMID 37373553, 2023).
cancer (120 papers, 2009 to 2026). A tumor composed of atypical neoplastic, often pleomorphic cells that invade other tissues. "VCP plays a role in endoplasmic reticulum-associated degradation and shows elevated expression in multiple cancer types, including that of the cervix." (PMID 40507244, 2025). "Suppression of the function of p97/VCP by using siRNA or specific inhibitors causes apoptosis and activation of caspase in human cancer cells." (PMID 39473740, 2024). "Given that hyperactive Akt counteracts chemotherapeutic-induced apoptosis, VCP inhibition presents a promising therapeutic avenue to exploit Akt-associated vulnerabilities in cancer cells by triggering paraptosis while safeguarding normal cells." (PMID 38218922, 2024). "The inhibition of the function of P97/VCP is known to cause rapid caspase activation and apoptosis in cancer cells." (PMID 37374283, 2023). "To date, elevated VCP expression has been identified in many cancer types and associated with patient outcomes, which is correlated with aggressiveness and drug resistance." (PMID 37606987, 2023). "Valosin‐containing protein (VCP) is closely associated with the invasion and metastasis of cancer cells." (PMID 35068042, 2022). "The overexpression of VCP has been associated with poor prognosis and increased metastasis, proving it valuable as a marker for the advancement of these cancers." (PMID 35841038, 2022). "Since cancer is associated with overexpression of VCP, and the disease is associated with gain of function variants in the VCP gene, it is predicted that VCP inhibitors potentially would be effective for treatment of both disorders." (PMID 35841038, 2022). "Prolonged exposure to CB5083 resulted in the acquisition of resistance in several cancer cell lines due to the emergence of mutations in VCP." (PMID 36196920, 2022). "The study included individuals known to have cancer from a large cohort of 231 patients from 106 families with familial VCP variants." (PMID 35841038, 2022). "Aberrant VCP regulation and function can cause cancer as well as several neurodegenerative diseases." (PMID 36196920, 2022). "It has been reported that the level of VCP is associated with the prognosis of many types of carcinomas." (PMID 35432524, 2022). "The mechanism of resistance to VCP inhibitors in cancer has been reported to be linked to VCP/p97 mutations." (PMID 34576340, 2021). "In this review, we summarized the progress of studies on VCP, in terms of its regulation of ER and mitochondrial function and its implications for the associated diseases, focusing on the cancers, heart disease, and neurodegenerative disorders." (PMID 32481679, 2020). "VCP expression is upregulated in most types of cancer, and the level of VCP expression is genitively associated with survival rates in patients." (PMID 32481679, 2020). "When ranked by significance levels, the top three KEGG terms linked to VCP/p97 expression were ‘metabolic pathways’, ‘pathways in cancer’, and ‘PI3K-Akt signalling pathway’." (PMID 30626938, 2019). "DBeQ, ML240, ML241 and CB-5083, selective and potent P97/VCP inhibitors, rapidly cause cancer cell death." (PMID 31671908, 2019). "Next, we looked to profile all mutations in VCP recorded in the cancer cell line encyclopedia (CCLE)." (PMID 31358864, 2019). "ERAD and VCP/p97 have been implicated in a multitude of human diseases, such as neurodegenerative diseases and cancer." (PMID 28322292, 2017). "Since p97/VCP is implicated in several diseases including cancer, modulators of p97/VCP can be therapeutic." (PMID 23226521, 2012). "We explored whether the preferential sensitivity of cancer cells to VCP inhibition is linked to oncogenic activation." (PMID 38218922, 2024).
cancer (continued). "Another enriched protein, encoded by the valosin-containing protein (also known as p97), was in the center node of the Wnt signaling pathway subnetwork and was demonstrated to be overexpressed in many cancer types and is regarded as a potential biomarker and therapeutic target." (PMID 37172717, 2023). "In addition, VCP has been implicated in a variety of metabolic processes at the gene expression level in a diverse range of cancer cell lines and in patient-derived MM cells." (PMID 37606987, 2023). "The ATPase p97 (also known as VCP, Cdc48) has crucial functions in a variety of important cellular processes such as protein quality control, organellar homeostasis, and DNA damage repair, and its de-regulation is linked to neuromuscular diseases and cancer." (PMID 37713320, 2023). "This suggests that cancer patients with gain of function VCP variants may potentially be more effectively treated with VCP inhibitors." (PMID 35841038, 2022). "Because gain of function variants in VCP are implicated in VCP disease, we hypothesize that an atypical distribution of malignancy types and a higher tendency to develop cancer may be found among our patients." (PMID 35841038, 2022). "A cell-permeable polypeptide derived from the ASPL UBX domain causes cancer cell death suggesting a yet unknown physiological role of VCP:ASPL hetero-tetramers." (PMID 36196920, 2022). "This review summarizes the role of VCP/p97 in different cancers and the advances in the discovery of small-molecule inhibitors with therapeutic potential, focusing on the challenges associated with cancer-related VCP mutations in the mechanisms of resistance to inhibitors." (PMID 34576340, 2021). "Thus, the increase of VCP in cancer cells would protect cells against death, while the deficiency of VCP in neurodegenerative disorders and heart diseases would induce cell damage and death, due to the loss of these functions." (PMID 32481679, 2020). "More importantly, we found that p97/VCP may be implicated in cancer cell migration properties, which are consistent with prominent findings stating that an increase in p97/VCP expression positively correlates with the invasiveness of most tumor cells." (PMID 32002125, 2020). "Moreover, VCP/p97 expression correlated with several processes that are linked to cellular metabolism and are frequently deregulated in cancer, such as ‘mTOR signalling pathway’ and ‘MAPK signalling pathway’." (PMID 30626938, 2019). "Cancer cells can rapidly acquire activating mutations in VCP that could bypass the effect of CB-5083." (PMID 29367883, 2017). "In addition, analysis of somatic mutations in VCP in tumor samples from TCGA data set indicated that frameshift mutations at codon 616 in VCP are frequently observed in cancer samples." (PMID 29367883, 2017). "Thus, cancer cell death following VCP inhibition was linked to inadequate fine-tuning of protein synthesis and activity of PPP1R15A/PP1c." (PMID 26720340, 2015). "Our results further strengthen the hypothesis that VCP gain-of-function variants are causal for the disease pathogenesis and that inhibition of VCP activity has translational potential, not only for cancer but also for VCP-associated myopathy." (PMID 34998409, 2022). "With experimental evidence of the up-regulation of ATPase activity in VCP disease causing variants, we propose that the VCP variant may be a key factor in the pathogenesis of these uncommon cancers, since VCP has been shown to be overexpressed in several different cancers." (PMID 35841038, 2022). "Another peculiarity of PI31 which may be relevant to cancer is its association with the VCP." (PMID 31456945, 2019). "Dysregulation of VCP activity contributes to the pathogenesis of neurodegenerative diseases and cancer, making it an important therapeutic target." (PMID 41793187, 2026). "VCP's role in promoting metastasis, particularly its influence on barrier disruption, has been reported in other cancer types." (PMID 39802400, 2025).
cancer (continued). "VCP is thought to be a possible cancer biomarker and therapeutic target because it is overexpressed in a variety of cancer types and positively correlates with a bad prognosis." (PMID 40583061, 2025). "VCP engages in a variety of cellular processes that are essential for cancer cell aggressiveness and survival through interactions with many cofactors." (PMID 40583061, 2025). "Nevertheless, these applications necessitate further investigation to determine the consistency of VCP’s mechanisms across different cancers." (PMID 39848960, 2025). "Given the crucial character of the TME in shaping cancer progression and response to therapy, understanding VCP’s contribution to this dynamic environment is crucial." (PMID 39848960, 2025). "The inhibition of VCP/p97 was initially proposed to induce cancer cell death through an increase in proteotoxic stress." (PMID 40593507, 2025). "Future studies should further explore the broad applications of targeting the VCP-G3P axis in other cancer types." (PMID 39848960, 2025). "PCA demonstrated a distinct separation between PCS cells and cancer cell lines, driven by elevated VCP and p16INK4a in cancer cells." (PMID 40507244, 2025). "The significant upregulation of MMP3 and MMP9 genes in VCP-overexpressing hCMEC/D3 cells suggests a potential role for VCP in modulating extracellular matrix dynamics and tissue remodeling processes, crucial for angiogenesis and cancer metastasis." (PMID 39802400, 2025). "Studies indicate that targeting the ERAD pathway, particularly VCP, offers a novel therapeutic avenue for cancers." (PMID 39820491, 2025). "The advancement of VCP inhibitors into phase I clinical trials for cancer acknowledge their potential for other debilitating and presently incurable disorders." (PMID 41355735, 2025). "The analysis revealed that VCP and p16INK4a were overexpressed in all cancer cell lines compared to PCS cells." (PMID 40507244, 2025). "CB-5083 (CB) mainly targets the D2 domain of VCP, and has demonstrated significant antiproliferative activity in cancer cells." (PMID 39489738, 2024). "Our study has illuminated the pivotal role of VCP as a molecular target for inducing paraptosis in cancer cells." (PMID 38218922, 2024). "VCP and VCP adaptors have targets for cancer treatment, as inhibiting VCP induces DNA damage and kills some types of cancer cells." (PMID 38891822, 2024). "Our study reveals that VCP inhibition leads to selective mTORC2 activation and mTORC1 inhibition in cancer cells." (PMID 38218922, 2024). "In conclusion, our study unveils the potential of VCP as a therapeutic target in cancer, emphasizing the selective vulnerability of cancer cells to VCP inhibition-induced paraptosis." (PMID 38218922, 2024). "VCP is essential for cancer cell proliferation, and its dysregulation has been implicated in several neurodegenerative diseases." (PMID 39585118, 2024). "Cancer cells with hyperactive mTORC2/Akt signaling are more vulnerable to VCP inhibition, making VCP an attractive target in this context." (PMID 38218922, 2024). "In summary, the selective cytotoxicity of VCP inhibition towards cancer cells can be attributed to the disruption of proteotoxic stress mitigation pathways involving the ATF4/DDIT4 axis and hyperactive mTORC2/Akt signaling." (PMID 38218922, 2024). "This process is further modulated by eIF3d-mediated translational recovery, which enhances proteotoxicity selectively in cancer cells undergoing paraptosis upon VCP inhibition." (PMID 38218922, 2024). "The role of differential VCP expression in the biology of different cancers, cancer therapeutic resistance and patient outcomes have been well studied." (PMID 38190410, 2024). "Together, these results suggest that VCP inhibition predominantly induces paraptosis as a cell death mechanism in cancer cells." (PMID 38218922, 2024). "Among these potential targets, VCP has emerged as both a prognostic biomarker and a prospective therapeutic target in cancer." (PMID 38218922, 2024).